NKX2-1 (NK2 homeobox 1)
Diseases named in the same sentence as NKX2-1 in open-access papers (continued):
Sharing a sentence is not in itself a finding about the gene and the disease.
schizophrenia (3 papers, 2016 to 2022). A major psychotic disorder characterized by abnormalities in the perception or expression of reality. "Genes identified to interact with NKX2-1/Nkx2-1 in human or rodent studies that have also been associated with susceptibility for development of schizophrenia or with the course of illness." (PMID 27064909, 2016). "Further indications of the possible role of NKX2-1 in the pathophysiology of schizophrenia came from studies of families affected by inactivating mutations in NKX2-1." (PMID 27064909, 2016). "Although Nkx2-1 has been shown to interact with a number of susceptibility genes for schizophrenia, most of these studies were performed in rodents and species-related differences may occur." (PMID 27064909, 2016). "Are dysregulated NKX2-1 associated processes specific to schizophrenia?" (PMID 27064909, 2016). "NKX2-1 interacts with a number of genes identified as susceptibility genes for schizophrenia." (PMID 27064909, 2016). "Therefore, we would propose that aberrant NKX2-1 function could result in a wide-ranging, multi-organ disorder that is the hallmark of classic untreated “Kraepelinian” schizophrenia." (PMID 27064909, 2016). "We correlate the symptoms seen in schizophrenia with the temporal and spatial activities of NKX2-1 in order to highlight promising future research areas." (PMID 27064909, 2016). "NKX2-1 governs multiple physiologic processes relevant to those somatic symptoms commonly seen in schizophrenia (as described)." (PMID 27064909, 2016). "To further explore the possible role of NKX2-1 in schizophrenia, we correlated the symptoms seen in schizophrenia with the temporal and spatial activities of NKX2-1, in order to highlight promising future research areas." (PMID 27064909, 2016). "Post-mortem studies in patients with schizophrenia can be performed to study cell populations developed from NKX2-1-expressing progenitors." (PMID 27064909, 2016). "Parenting behaviors, which are also mediated through the Nkx2-1-expressing neuroendocrine social-reproductive network in rodents, have been a major concern for female schizophrenia patients after giving birth." (PMID 27064909, 2016). "The possible involvement of NKX2-1 in the pathogenesis and pathophysiology of schizophrenia is fully compatible with the two-hit hypothesis, underscoring the importance of environmental factors in this disease." (PMID 27064909, 2016). "NKX2-1 may be involved in core, dose-sensitive, molecular pathways that are deregulated in schizophrenia." (PMID 27064909, 2016). "We suggest that NKX2-1 may lie at the core of several dose dependent pathways that are dysregulated in schizophrenia." (PMID 27064909, 2016). "Accordingly, NKX2-1 may lie at the core of several dose dependent pathways that are dysregulated in schizophrenia." (PMID 27064909, 2016). "Although these findings may suggest that NKX2-1-derived Cajal-Retzius and interstitial cells are dysfunctional in patients with schizophrenia, it is important to bear in mind that these cell populations are heterogeneous, and have diverse molecular origins." (PMID 27064909, 2016). "However, patients with schizophrenia certainly have brain dysfunctions that involve the progeny of NKX2-1 expressing progenitor cells." (PMID 27064909, 2016). "The wide range of masking behaviors that are affected in schizophrenia indicate that the Nkx2-1 expressing neural network may be dysfunctional." (PMID 27064909, 2016). "Knowledge of the processes that involve NKX2-1 may be of value in devising future treatment strategies for schizophrenia, including pharmacologic approaches, deep brain stimulation, and, potentially, stem cell-based treatments." (PMID 27064909, 2016). "This opens the possibility that abnormalities seen in early visual processing in schizophrenia might be influenced by Nkx2-1 expressing ipRGCs." (PMID 27064909, 2016).
schizophrenia (continued). "NKX2-1 also plays a central role in neurodevelopment and is essential for the formation and function of subgroups of neurons, glia, and functional neural networks that are affected in schizophrenia." (PMID 27064909, 2016). "We have used a “bottom-up” approach and tracked a developmental trajectory from embryology to physiological processes and behavior and recognized that the transcription factor NK2 homeobox 1 (NKX2-1) possesses properties of particular interest for schizophrenia." (PMID 27064909, 2016). "Molecular pathway analyses then indicated that processes related to neurodevelopment, immunity, neurotransmission, gene expression, and oxidative stress were all involved in the pathogenesis of schizophrenia; these are all strikingly similar to those processes involving NKX2-1." (PMID 27064909, 2016). "By linking NKX2-1 findings to electrophysiology, such studies may contribute to an improved understanding of brain oscillations in schizophrenia." (PMID 27064909, 2016). "However, until results of research into the role of NKX2-1 in schizophrenia, including comparisons with other highly heritable disorders are published, our proposal must be regarded as an educated hypothesis." (PMID 27064909, 2016). "The scientific literature gives no indication that a large proportion of people with schizophrenia could carry a mutation or copy number variation in the NKX2-1 gene." (PMID 27064909, 2016). "NKX2-1 conducts key functions at the interface of the brain, the neuroendocrine system, and the immune system, and may be an important mediator of aberrant cross-communication among these systems in schizophrenia." (PMID 27064909, 2016). "Nkx2-1's prominent expression in this network indicates that this transcription factor may be an important modulator of network activity, and, as a result, could influence the physiological processes and social behaviors that are disturbed in patients with schizophrenia." (PMID 27064909, 2016). "NKX2-1 expression patterns have not been explored either in schizophrenia or in any other neurodevelopmental or psychiatric disorder." (PMID 27064909, 2016). "Interestingly, FOXP2, a candidate gene for schizophrenia, interacts with NKX2-1 in the human lung, and is co-expressed with Nkx2-1 in the posterodorsal medial amygdala nucleus in mice." (PMID 27064909, 2016).
thyroid hypoplasia (3 papers, 2014 to 2024). Thyroid hypoplasia is a form of thyroid dysgenesis characterized by incomplete development of the thyroid gland that results in primary congenital hypothyroidism, a permanent thyroid deficiency that is present from birth. "It is important to note, however, that thyroid ultrasonography has particular significance in NKX2-1-RD due to its ability to precisely measure the dimensions of the thyroid gland of the patients presenting reduced thyroid volume with thyroid hypoplasia." (PMID 38990976, 2024). "Not formally quantitating thyroid gland size might have failed to ascertain cases with mild thyroid hypoplasia, harboring mutations in some thyroid-dysgenesis associated genes (eg, PAX8, Nkx2–1)." (PMID 27525530, 2016).
acute lymphoblastic leukemia (2 papers, 2017 to 2024). Leukemia with an acute onset, characterized by the presence of lymphoblasts in the bone marrow and the peripheral blood. "Sertraline selectively inhibited the proliferation of serine synthesis dependent breast cancer, RPL10 R98S T-cell acute lymphoblastic leukemia (T-ALL) cells, and NKX2-1 T-ALL and NSCLC cells." (PMID 38160212, 2024). "T-cell acute lymphoblastic leukemia (T-ALL) cells represent developmentally arrested T-cell progenitors, subsets of which aberrantly express homeobox genes of the NKL subclass, including TLX1, TLX3, NKX2-1, NKX2-5, NKX3-1 and MSX1." (PMID 28151996, 2017).
adenoma (2 papers, 2016 to 2022). A neoplasm arising from the epithelium. "As anticipated, lung tumors in KT;Lkb1XTR/XTR mice were adenomas and adenocarcinomas that express NKX2-1, a marker of adenocarcinoma differentiation, with only rare clusters of poorly differentiated cancer cells at late time points 36,43,44." (PMID 35228570, 2022).
cervical carcinoma (2 papers, 2016 to 2021). A carcinoma arising from either the exocervical squamous epithelium or the endocervical glandular epithelium. "In particular, the cervix carcinoma produced high levels of NKX2-1, NKX2-2 and NKX2-5." (PMID 27876760, 2016).
colorectal cancer (2 papers, 2010 to 2016). A primary or metastatic malignant neoplasm that affects the colon or rectum. "For example, an abnormal dopaminergic commissure at the level of the diencephalon traveling through the hypothalamus from the MFB has been previously reported in the Slit1/Slit2 double KO, the Deleted in colorectal cancer (Dcc) KO, and the NK2 Homeobox 1 (Nkx2.1) KO mice." (PMID 27648578, 2016).
emphysema (2 papers, 2012 to 2023). "In addition, increased expression of TTF-1/NKX2-1 in alveolar type II cells has been found to induce dose-dependent alterations in alveolar morphology, epithelial cell hyperplasia, emphysema, and pulmonary inflammation." (PMID 36672632, 2023).
Esophageal atresia (2 papers, 2022). A developmental defect resulting in complete obliteration of the lumen of the esophagus such that the esophagus ends in a blind pouch rather than connecting to the stomach. "Mouse models with reduced expression Sox2 or absence of Nkx2-1 resulted in separation defects, resembling the human congenital condition called tracheoesophageal fistula (TEF), where the airway is connected with the stomach and/or esophageal atresia (EA), a short and blunted esophagus." (PMID 36299482, 2022).
gastric adenocarcinoma (2 papers, 2024 to 2026). "We have previously reported that gastric adenocarcinoma of the fundic gland type shows high expression levels of SFTPB and SFTPC, both of which are transactivated by the ectopic expression of NKX2-1/TTF1." (PMID 37962678, 2024).
glioblastoma (2 papers, 2017 to 2024). The most malignant astrocytic tumor (WHO grade IV). "The correlation between DLL3 and NKX2-1 in glioblastoma is notable as rovalpituzumab tesirine is indicated for glioblastoma in an ongoing basket trial (NCT 02709889) and requires DLL3 expression for enrollment." (PMID 29088717, 2017). "We further compared the correlation between TTF1 and DLL3 protein in cell lines, and NKX2-1 and DLL3 mRNA in cell lines, an additional SCLC patient cohort and a cohort of glioblastoma patient samples and found significant correlations in each dataset." (PMID 29088717, 2017).
Immunodeficiency (2 papers, 2024 to 2025). Failure of the immune system to protect the body adequately from infection, due to the absence or insufficiency of some component process or substance. "Single articles describe various symptoms that occur in patients with NKX2-1 gene mutation: erectile dysfunction; immunodeficiency; ligamentous laxity; pes cavus; genitourinary abnormalities; congenital heart defect; or hypodontia." (PMID 38916623, 2024).
invasive carcinoma (2 papers, 2023). A carcinoma that is not confined to the epithelium, and has spread to the surrounding stroma. "Tumors originating from AT2 cells continuously showed an NKX2-1+/SOX2– pattern from early hyperplastic lesions to invasive carcinoma (left)." (PMID 38093367, 2023). "Following CC10-Cre infection in the KPU lung, hyperplasia at bronchioles initially exhibited positive expression for both factors; however, NKX2-1 expression was subsequently downregulated at the carcinoma in situ (CIS) stage and remained consistently negative in invasive carcinoma (right)." (PMID 38093367, 2023).
leukemia (2 papers, 2018 to 2019). A malignant (clonal) hematologic disorder, involving hematopoietic stem cells and characterized by the presence of primitive or atypical myeloid or lymphoid cells in the bone marrow and the blood. "Conversely, the PLXND1, PLCB4, HOXA9, HOXA10, TLX3, and NKX2‐1 genes had higher expression in the CIMP+ subgroup, compared to the normal T cells and CIMP− leukemias." (PMID 30575306, 2019). "For example, GATA1 partners with HNF1 in hematopoietic progenitor cells; with PPARA:RXRA in leukemia; with SRF, CDX and FOXP3 in primary T-cells; with SRY, NKX2-1, FOXF1, OCT4 and ZBTB16 in differentiated ESCs and with TAL1:TCF3 motif co-occurring in various fibroblasts." (PMID 30142147, 2018).
mantle cell lymphoma (2 papers, 2018). Mantle cell lymphoma is a rare form of malignant non-Hodgkin lymphoma affecting B lymphocytes in the lymph nodes in a region called the ``mantle zone''. "Deregulated NKL homeobox genes have been described in B-cell malignancies as well including MSX1 in mantle cell lymphoma, NKX2-1 in DLBCL, and NKX2-3 in marginal zone B-cell lymphoma." (PMID 29581848, 2018).
microcephaly (2 papers, 2014 to 2023). A congenital or acquired developmental disorder in which the circumference of the head is smaller than normal for the person's age and sex. "In this study, I focus on several homeobox genes (ARX, LHX2, MEIS2, NKX2-1, OTX1, OTX2, and PAX6) implicated in the pathogenesis of microcephaly." (PMID 38094004, 2023). "In another report on two siblings with hypothyroidism and respiratory failure due to the 14q12-13.3 deletion, both were reported to have postnatal microcephaly, further implicating the potential role of NKX2-1 in microcephaly accompanying brain–thyroid–lung syndrome." (PMID 38094004, 2023).
oral cancer (2 papers, 2021 to 2024). "This polymorphism may influence the motif for potential binding of transcription factor LUN-1, MAF oncogene family, and a cancer stem cell regulator NK2 homeobox 1 (Nkx2), previously associated with oral cancer in vitro." (PMID 38850110, 2024).
pancreatic ductal adenocarcinoma (2 papers, 2018 to 2021). An infiltrating adenocarcinoma that arises from the epithelial cells of the pancreas. "It is interesting to consider these results in the context of two recent studies where the combinatorial effect of Palbociclib and MEK inhibitor (Trametinib) was tested in models of KRAS-driven NKX2-1-positive LUAD and in KRAS-driven pancreatic ductal adenocarcinoma (PDAC)." (PMID 33821796, 2021).
Arthritis (1 paper, 2025). Inflammation of a joint. "In addition to the BACH1 discovery, the highest ranked TFs in RA FLS included two homeobox genes (NKX2-1 and HOXA1) not previously implicated in arthritis." (PMID 39467637, 2025).
ataxic cerebral palsy (1 paper, 2024). A form of cerebral palsy caused by damage to cerebellar structures. "Therefore, NKX2-1-related disorders could be mistaken for ataxic cerebral palsy." (PMID 38916623, 2024).
athyreosis (1 paper, 2025). Athyreosis is a form of thyroid dysgenesis characterized by complete absence of thyroid tissue that results in primary congenital hypothyroidism, a permanent thyroid deficiency that is present from birth. "TD represents approximately 80–85% of CH cases and includes conditions such as ectopy, athyreosis, and orthopic hypoplasia, which are rarely linked to mutations in transcription factor genes like TSHR, PAX8, and NKX2-1." (PMID 40981308, 2025).
Dyskinesia (1 paper, 2020). A movement disorder which consists of effects including diminished voluntary movements and the presence of involuntary movements. "We found that the methylation status of the DMRs of En1 and Nkx2-1 was negatively associated with their transcriptional and translational levels and that alteration of the DNA methylation status of DMRs and the corresponding transcription occurred before dyskinesia in SCA3/MJD mice." (PMID 33411688, 2020).
Fanconi Anaemia (1 paper, 2022). "These include variants in genes encoding FANCE, a subunit of the Fanconi Anaemia (FA) nuclear complex; NKX2-1, a transcription factor and negative regulator of the NF-κB signalling pathway; and other recognized oncogenes JAK2, PRDM16, BMPR1A and tumor-suppressor genes KMT2C, FAT4, and LRP1B." (PMID 35954343, 2022).
Lewis lung carcinoma (1 paper, 2024). "NKX2‐1 was knocked down in murine Lewis lung carcinoma cells (LL2) expressing luciferase reporter and eGFP." (PMID 39113226, 2024).
lung adenosquamous carcinomas (1 paper, 2023). "Our analyses of 93 human lung adenosquamous carcinomas showed that the signatures for the Wnt signaling were negatively correlated with the AST score, similar to the NKX2-1 signature." (PMID 36627278, 2023).
neuroblastoma (1 paper, 2011). Neuroblastoma (NB) is the most common solid, extracranial childhood tumor. "SK-N-SH neuroblastoma cell was shown to express RET, NKX2-1, PHOX2B, but not SOX10, PAX3." (PMID 21677782, 2011).
pneumonitis (1 paper, 2013). An inflammatory process affecting the lung parenchyma. "The DS1-treated dogs also had less pneumonitis detected by CT imaging and an increased number of TTF-1 (thyroid transcription factor 1, NKX2-1) positive cells in the bronchioli and alveoli compared to control dogs." (PMID 23520463, 2013).
thyroid abnormalities (1 paper, 2024). "Several studies advocate for the widespread screening of newborns to detect thyroid abnormalities and, upon confirmation, recommend further investigation into genetic etiologies, including NKX2-1-RD." (PMID 38990976, 2024).
viral infection (1 paper, 2016). "When exposed to an immune challenge corresponding to viral infection during the neonatal period, the transgenic mice exhibited impaired Nkx2-1-associated behaviors, such as fear memory, social recognition, and social interaction." (PMID 27064909, 2016).